TLR2 (toll like receptor 2)
Diseases named in the same sentence as TLR2 in open-access papers (continued):
Sharing a sentence is not in itself a finding about the gene and the disease.
lupus (39 papers, 2013 to 2025). "The relevance of TLR2 in arterial thrombosis is complemented by a clinical study in systemic lupus erythematosus patients, which has identified single nucleotide polymorphisms in the Tlr2 gene that were linked to arterial thrombosis." (PMID 32998468, 2020). "Previous studies had shown that patients with SLE had lower expression of TLR2 in monocytes in comparison to healthy controls, but this is the first study to describe it as a major risk factor for infection in lupus patients." (PMID 30692998, 2018). "Moreover, TLR2-deficiency significantly reduced anti-DNA/nucleosome antibodies, renal disease, and IL-6 production in a pristane-induced lupus mouse model." (PMID 31354738, 2019). "Based on the pristane-induced lupus model is also performed in B6 background, one possibility for these contradicting findings in TLR2−/− mice is that TLR2 gene polymorphism between B6 and MRL mice strains may contribute to the different outcomes to TLR2 deficiency in lupus development." (PMID 26068236, 2015). "In the lupus-prone model, TLR2 or TLR4 knockdown downregulated the antinuclear antibody levels and alleviated disease symptoms." (PMID 37667233, 2023). "Studies from our laboratory proved that in pristane-induced lupus, TLR2 is required for autoantibody production and development of renal disease." (PMID 31266174, 2019). "In human overt SLE, TLR2 mRNA is upregulated in PBMCs but in young lupus patients (median age of 13 years at the time of enrolment) monocyte TLR2 and-4 cell surface expression can be even reduced when examined by flow cytometry." (PMID 29650017, 2018). "TLR2 plays an important role in several different autoimmune diseases, including lupus and rheumatoid arthritis." (PMID 30671484, 2018). "Overall, these results suggest that TLR2 and TLR9 are a new couple of pathogenic receptors involved in lupus progression that can be tested as therapeutic targets." (PMID 28410407, 2017). "In lupus-prone mice, TLR2 activation triggers lupus nephritis, whereas TLR2 knockout attenuates lupus-like symptoms." (PMID 28588585, 2017). "Only few reports have studied the role of TLR2 in lupus pathogenesis, focusing mostly on the damaging effects of lipoproteins in the kidney." (PMID 28410407, 2017). "In both B6/lpr mice and pristine-induced lupus mice, TLR2 knockout resulted in decreased autoantibody levels and ameliorated lupus-like symptoms." (PMID 26648937, 2015). "In this review, roles of B cell-intrinsic TLR2, 4, 7, 8 and 9 signals are discussed during lupus pathogenesis in both mouse model and patients." (PMID 26068236, 2015). "This review focuses on recent evidence regarding the involvement of B cell-intrinsic TLR signals during lupus pathogenesis with an emphasis on the contribution of B cell-specific TLR2, 4, 7, 8 and 9 to lupus progression." (PMID 26068236, 2015). "Moreover, TLR2 is required for autoantibody production and development of renal disease in pristane-induced lupus." (PMID 36353645, 2022). "In patients with systemic lupus erythematosus and concurrent active nephritis, the level of TLR2 in peripheral blood T cells and of TLR4 in B cells and monocytes was increased, and the rate of protein excretion in the urine was associated with TLR expression in these cells." (PMID 32079183, 2020). "In addition, the in vitro stimulation of TLR2 on CD4+ T cells from patients with systemic lupus erythematosus increased cytokine production." (PMID 32079183, 2020). "Moreover, in TLR2- and TLR4-deficient C57BL/6lpr/lpr, as well as pristane-injected TLR4-deficient animals, development of murine lupus, was mitigated, while TLR2 and TLR4 activation enhanced disease." (PMID 31266174, 2019). "Also, HMGB1, a DNA-binding protein, and lupus autoantigen, released under inflammatory conditions can induce NF-κB activation in a TLR2 and TLR4-RAGE-dependent manner in mononuclear phagocytes and neutrophils as well as in mesangial cells." (PMID 29650017, 2018).
lupus (continued). "Moreover, high levels of soluble TLR2 were shown in the sera of patients affected by psoriasis and systemic lupus erythematosus, diseases in which innate immunity plays a major pathogenetic role." (PMID 25767508, 2015). "TLR7/9-activated IRF5 elevates IL-10 in systemic lupus erythematosus (SLE) models, contrasting with its pro-inflammatory role in TLR2/4-mediated pathways." (PMID 40980176, 2025). "For instance, in patients with systemic lupus erythematosus (SLE), autoantibodies directed against double—stranded DNA (dsDNA) and nucleosomes can trigger the activation of DCs via TLR2 when complexed HMGB1." (PMID 40877572, 2025). "However, like the deficiency of TLR4, in MRL/lpr mice, TLR2 deficiency did not affect lupus pathogenesis, possibly due to mouse strain differences." (PMID 26648937, 2015). "However, further studies on MRL-Faslpr/lpr mice reveal that TLR2 deficiency has no impact on lupus pathogenesis." (PMID 26068236, 2015). "Decreased anti-dsDNA antibodies were observed in TLR2 and TLR4 knockout C57BL/6 (lpr/lpr) mice; and autoantibodies were induced by LPS stimulation through the TLR4-dependent cell signaling pathway in lupus-prone mice." (PMID 30150778, 2018). "Consistent with previous studies in lupus models, treated animals displayed reduced expression of TLR1, TLR2, TLR3, TLR4, and TLR9 in salivary tissue." (PMID 30671484, 2018). "Second, in a lupus mouse model, the deletion of TLR4 or TLR2 (to a lesser extent) decreases the levels of autoantibodies, and subsequently ameliorates the disease symptoms." (PMID 28769820, 2017). "In pristane-induced lupus mouse model, TLR2−/− mice show lower ANA levels and reduced lupus pathogenesis, together with a reduced level of HMGB1, a well-known endogenous TLR ligand." (PMID 26068236, 2015). "We therefore decided to examine if the findings suggesting a role for TLR2 and TLR4 in the milder lupus models would be confirmed in MRLlpr mice." (PMID 24086313, 2013). "Although TLR2 is part of the innate immune response and is vital for the defense against viruses, its activation has been shown to be involved in various autoimmune diseases, including RA, Sjögren’s syndrome, MS, systemic sclerosis and systemic lupus erythematosus (SLE)." (PMID 36851614, 2023). "Another study also reported that Pam3CSK4, a TLR2 agonist, could stimulate SLE patient-derived monocytes to differentiate into M2-like macrophages, leading to an improved outcome of murine lupus." (PMID 33584646, 2020). "However, the expression of Anxa4 and TLR2 were increased in M-MDSCs, INK128 could inhibit Anxa4 and TLR2 expression in M-MDSCs in pristane-induced lupus mice." (PMID 34282122, 2021). "Expression levels of TLR2, TLR7, TLR9, IFN-alpha, and LY6E (Sca-1) mRNAs in SLE patients are significantly higher than healthy controls, indicating contribution of TLR-MyD88 signaling pathways in the pathogenesis of human lupus." (PMID 31354738, 2019). "Therefore we cannot be sure that combined deficiency of TLR2 and TLR4 would not have resulted in protection from lupus in MRLlpr mice where none was seen with deficiency in just one receptor." (PMID 24086313, 2013). "Recent work has suggested that TLR2 and TLR4 may also play a role in murine lupus in the absence of exogenous ligand administration." (PMID 24086313, 2013).
type 2 diabetes (39 papers, 2009 to 2026). "TLR2 gene expression is associated with increased innate immune response in immune disorders and type 2 diabetes as TLR2 levels are inversely associated with glucose transport." (PMID 36768984, 2023). "Since more than 90 % of studies reported that TLR2 is positively associated with type 2 diabetes and its complications, it seems that the inflammatory effects of TLR2 during the condition are predominant." (PMID 28536605, 2016). "Accordingly, the altered expression and functions of TLR2 and its intracellular molecular signaling may be associated with the mechanisms that result in the progression and pathogenesis of type 2 diabetes and its related complications." (PMID 28536605, 2016). "Moreover, via upregulation of IL-6 and osteopontin, TLR2 causes impaired insulin-mediated brain activities, which are an early step in the development toward type 2 diabetes." (PMID 28536605, 2016). "Previous studies have linked inducible and increased expression of TLR2 in PBMC and SAT of obese individuals with type 2 diabetes." (PMID 30941121, 2019). "High doses of insulin (100 IU/ml), such as those seen in cases of type 2 diabetes, also increased IL-6 and decreased TLR2 expression." (PMID 28536605, 2016). "TLR2 plays crucial roles in the initiation and pathogenesis of type 2 diabetes and related complications." (PMID 28536605, 2016). "Another study revealed that although type 2 diabetes patients had higher serum levels of IL-6, the mRNA levels of TLR2 were lower than in healthy subjects." (PMID 28536605, 2016). "Here, we review recent data on the important roles and status of TLR2 in type 2 diabetes and related complications." (PMID 28536605, 2016). "It has also been documented that oxidized LDL, which is produced during type 2 diabetes, induced expression of TLR2 in macrophages." (PMID 28536605, 2016). "Another study also identified that TLR2 not only participates in the development of type 2 diabetes but is also involved in the pathogenesis of related vascular complications." (PMID 28536605, 2016). "Increased TLR4 expression leads to type 2 diabetes by reducing insulin secretion by β-cells and together with TLR2 and TLR9 contribute to the development of neurological disorders like schizophrenia and autism." (PMID 27307950, 2016). "Collectively, it appears that TLR2 plays remarkable roles in the development of type 2 diabetes and related complications." (PMID 28536605, 2016). "Accordingly, CpGs methylation in the promoter of the TLR2 gene was significantly decreased in type 2 diabetes patients in comparison to the levels for the controls." (PMID 28536605, 2016). "The prior data demonstrate a correlation between TLR2/4 expression and BMI in subjects with type 2 diabetes; however, the exact mechanism by which these two clinical predictors are interlinked remains undefined." (PMID 23191980, 2012). "Similarly, human β cells express TLR2 transcripts, with significantly elevated levels observed in individuals with type 2 diabetes, suggesting a conserved role for TLR2 in β-cell stress sensing and immune regulation." (PMID 40969771, 2025). "In addition, TLR2 expression and functional activation are increased in recently diagnosed type 2 diabetes, contributing to the proinflammatory state." (PMID 32685087, 2020). "TLR2 expression arises in the Type 2 diabetes patients, and the TLR2 −/− knockout model." (PMID 31752797, 2019). "These correlations might relate to functions of Tlr2 in other processes such as the control of diabetes type II by gut microbiota." (PMID 31747871, 2019). "Therapeutic approaches involving modulation of the expression of TLR2 and related signaling molecules could be considered as novel approaches for the treatment of type 2 diabetes." (PMID 28536605, 2016). "The phagocytic cells of type 2 diabetes patients have also upregulated TLR2." (PMID 28536605, 2016). "A few studies demonstrated that TLR2 expression decreased during type 2 diabetes." (PMID 28536605, 2016).
type 2 diabetes (continued). "TLR2 also recognizes some DAMPs as endogenous ligands, including human glycosaminoglycan hyaluronan, β-defensin-3, heat shock proteins and high mobility group box 1 protein, some of which are released during inflammatory diseases like type 2 diabetes." (PMID 28536605, 2016). "Several DAMPs are released during type 2 diabetes, so it may be hypothesized that TLR2 is significantly involved in its progression." (PMID 28536605, 2016). "Interestingly, a link between TLR2 and TLR4 polymorphisms and Type 2 diabetes has been documented, suggesting that TLRs may play a causative role in diabetes." (PMID 27478851, 2016). "Therefore, TLR2 may participate in the development and pathogenesis of immune-related diseases, including type 2 diabetes." (PMID 28536605, 2016). "TLR2 also recognizes PAMPs such as exogenous microbial ligands, so it may be hypothesized that microbial infections could be important factors in the development of type 2 diabetes and may also participate in the pathogenesis of the disease." (PMID 28536605, 2016). "TLR2 and TLR4 expression and their ligands, signaling, and functional activation are increased in diagnosed type 2 diabetes and contribute to the proinflammatory state." (PMID 32824985, 2020). "Reduced methylation in the promoters of proinflammatory genes TLR2 and FFAR3 is correlated with reduced abundance of Faecalibacterium prausnitzii in type 2 diabetes patients." (PMID 28388917, 2017). "We recently reported that TLR2 and TLR4 localize on the glomerular endothelium in the glomeruli of STZ-induced type 1 diabetic mice and in high fat diet feed-induced type 2 diabetic mice." (PMID 29018490, 2017). "Other studies have shown the increased expression of TLR2 and TLR4 in conventional insulin resistance target tissues like skeletal muscle and adipose tissue of Type 2 diabetics." (PMID 27478851, 2016). "In another study, with type 2 diabetic patients, in which TLR expression in mononuclear cells was monitored in response to low-dose insulin infusion, a further relationship between TLR2 and TLR4, and insulin homeostasis was identified." (PMID 21356084, 2011). "However, both TLR2 and TLR4 expression was increased on monocytes in patients with type II diabetes." (PMID 32933213, 2020). "We also observed the in vitro effect of HG on the upregulated expression of TLR-2 and TLR-4 on the cell surface of primary monocytes from healthy subjects, similar to recently diagnosed type 2 diabetic patients, supporting the upregulation of TLRs in the presence of HG concentrations." (PMID 31815150, 2019). "Our results showed that the subjects with type-2 diabetes had significantly elevated mRNA levels of TLR2 and TLR4 as compared with non-diabetic obese subjects." (PMID 23191980, 2012). "Therefore, TLR2 and TLR4 may be a promising therapeutic target to prevent or retard DNP in type 2 diabetic patients." (PMID 33442388, 2020). "Moreover, it can be suggested that TLR2 and TLR4 may be a promising therapeutic targets to prevent or retard the DNP in type 2 diabetic patients." (PMID 33442388, 2020). "There have not been many studies on the variation of the TLR2 gene in type 2 diabetes are rare." (PMID 28536605, 2016). "Additionally, they showed that obese type 2 diabetes patients had higher expressions of TLR2 in comparison to obese patients without type 2 diabetes." (PMID 28536605, 2016). "However, in patients with type 2 diabetes and confirmed biopsy, diabetic kidney disease has been found to increase TLR4 expression on renal tubules as opposed to TLR2." (PMID 32933213, 2020).
Alzheimer disease (37 papers, 2010 to 2025). A progressive, neurodegenerative disease characterized by loss of function and death of nerve cells in several areas of the brain leading to loss of cognitive function such as memory and language. "Reported associations of TLR2 genetic variants with Alzheimer’s disease, onset age of bipolar disorder, and cognitive function in schizophrenia are highly suggestive of genetically driven interindividual ability to modulate neuroinflammatory processes." (PMID 26415953, 2016). "SNP rs7656500 (uLR β^G=0.79,p=0.01 and pMLE-DX β^G=6,p=0.02) locates at the intergenic region between KIAA0922 and TLR2 at Chromosome 4, and is 163k upstream and 144k downstream of rs727153 and rs1466662, respectively, which were reported associated with Alzheimer’s disease in two studies." (PMID 30133451, 2018). "For example, TLR2 has been implicated as a primary receptor for amyloid β peptide, and this interaction is thought to facilitate an increase in neuroinflammation during Alzheimer’s disease." (PMID 30596651, 2018). "Moreover, associations between the TLR2 genetic diversity and Alzheimer’s disease or cognitive function in schizophrenia are highly suggestive of genetically-driven inter-individual ability to modulate neuroinflammatory processes." (PMID 25790282, 2015). "Besides these observations, association of TLR2 genetic diversity either with Alzheimer’s disease or with cognitive function in SZ suggests that inter-individual liability to modulate neuro-inflammation may be genetically driven." (PMID 27207565, 2016). "In both human brains and animal models of Alzheimer's disease, there is an upregulation of TLR2, TLR4, and CD14 expression." (PMID 38698886, 2024). "* Alzheimer's disease (AD): increased expression of TLR2, TLR4, and CD14 has been observed in human brains and animal models of AD." (PMID 38698886, 2024). "In particular, microglia, the main cellular component of the innate immune system in the brain, express high levels of TLR2, making them a valuable target in the initiation, progression, and preservation of Alzheimer’s disease." (PMID 37569837, 2023). "This study is focused on the potential roles of various TLRs in various neurodegenerative diseases such as Parkinson’s disease (PD) and Alzheimer’s disease (AD), namely TLR2, TLR3, TLR4, TLR7, and TLR9 in AD and PD in human beings and a mouse model." (PMID 34827372, 2021). "TLR2 was found to be upregulated in the microglia surrounding amyloid β (Aβ) plaques, both in human post mortem brains as well as Alzheimer’s Disease (AD)mouse models." (PMID 34827372, 2021). "Accumulating data suggest a central role for brain microglia in mediating cortical neuronal death in Alzheimer’s disease (AD), and for Toll-like receptor 2 (TLR2) in their toxic activation." (PMID 32059733, 2020). "We have found that TLR2 and MyD88 levels are elevated in the hippocampus and cortex of patients with Alzheimer’s disease (AD) and in a 5XFAD mouse model of AD." (PMID 29990310, 2018). "Recently, TLR4 and TLR2 have been shown to play a significant role in neuroinflammation occurring during Alzheimer's disease." (PMID 28790798, 2017). "The previous study reported that CD14 and TLR2 were upregulated in animal models of various neurodegenerative diseases, including Alzheimer’s disease (AD), Parkinson’s disease (PD), and ALS." (PMID 27812125, 2016). "Moreover, it is well known that TLR2 accelerates the pathology of neurological disorders such as Alzheimer’s disease (AD), Parkinson’s disease (PD), and neuroinflammation." (PMID 39057755, 2024). "Toll-like receptor-2 (TLR2), a member of the TLR family, plays an important role in the initiation and regulation of immune/inflammation response, which is a critical mechanism underlying Alzheimer’s disease (AD)." (PMID 31509519, 2019).